BDNF (brain derived neurotrophic factor)
Diseases named in the same sentence as BDNF in open-access papers (continued):
Sharing a sentence is not in itself a finding about the gene and the disease.
tumor (continued). "Accordingly, CaMKK2 is critical for brain-derived neurotrophic factor (BDNF) expression in neurons, which has already been seen to contribute to pro-tumor mitogenic functions in high-grade gliomas." (PMID 36309495, 2022). "The BDNF levels were found to be higher in CMF alone treated tumor-bearing animals and were significantly reduced in all treatment groups." (PMID 35197512, 2022). "At the same time, the interaction between BDNF and TrkB is also believed to regulate tumor cell invasion and drug resistance, leading to poor prognosis." (PMID 36406133, 2022). "BDNF was reported to be involved in tumor pathogenesis, exerting carcinogenic effects in different types of cancer, including lung, promoting proliferation and invasion of lung squamous cell carcinoma." (PMID 36361620, 2022). "Elevated BDNF levels were observed in the tumor control group compared to the normal control group (p < 0.05)." (PMID 35197512, 2022). "Exogenous (and presumably pineal-derived circadian) melatonin has significant impacts on tumor microenvironment immune and tumor cells, often with some contrasting effects compared to TrkB activation by BDNF." (PMID 36613754, 2022). "Recently, Wang and colleagues have reported a role for TrkB-expressing cancer stem cells in GBM progression in response to BDNF stimulation by differentiated tumour cells." (PMID 35473984, 2022). "To elucidate the molecular mechanisms underlying the role of the BDNF/TRKB pathway in the progression of PGC, we established one PGC cell and two CAF lines from human tumor tissues excised from patients with PGC." (PMID 36266462, 2022). "The TrkB/BDNF signaling pathway is also involved in a variety of physiological functions such as tumor angiogenesis, proliferation, metastasis, and invasion and is closely related to the invasion and metastasis of a variety of malignant tumors." (PMID 36033826, 2022). "Neurotrophic factors such as nerve growth factor (NGF), and brain-derived neurotrophic factor (BDNF), are considered drivers of neurogenesis during development and regeneration, playing a key role in the crosstalk between tumor cells and nerves." (PMID 36406133, 2022). "As the tumor benefits from the BDNF-mimicking effects of NAS, factors that increase the NAS/melatonin ratio, including the AhR, P2Y1r and mGluR5 become other direct and indirect targets of the tumor in its quest for survival." (PMID 36613754, 2022). "During bone metastases, growth factors including NGF and brain-derived neurotrophic factor (BDNF) are released from stromal cells, immune cells (e.g., mast cells, macrophages) and tumor cells." (PMID 35668080, 2022). "BDNF at TrkB regulates MSC development, whilst the capacity of MSC to secrete BDNF will have significant impacts in the tumor microenvironment." (PMID 36613754, 2022). "On the opposite side, the marked repression of BDNF in the KDM5CHigh subgroup suggests a possible direct role of KDM5C in the promoter’s demethylation in these tumor samples." (PMID 36142158, 2022). "It has been shown that catecholamines stimulate ovarian cancer cells via β3-adrenergic receptors, and cancer cells, in turn, produce BDNF to promote tumor innervation, forming a feed-forward loop." (PMID 36077804, 2022). "In both cancer types, the postoperative serum BDNF levels significantly declined only in patients with smaller tumours, of below the median volume." (PMID 34395067, 2021). "They found a positive correlation between BDNF and TrkB messenger RNA (mRNA) expression (p < 0.005) and significant upregulation of both proteins in >50% of tumor specimens, when compared to normal mucosa." (PMID 34885121, 2021). "We next estimate the ROC-AUC value with the best fit multivariate Cox models using CD66b, BDNF, CysLT1R expression in tumor tissues and the significant clinical factors (gender, LNM, TNM) from the univariate model." (PMID 34771682, 2021).
tumor (continued). "Mechanistically, EE increased the neurothrophic brain-derived neurotrophic factor (BDNF) in the hypothalamus of tumor-bearing mice that, in turn, selectively reduced letin production via sympathoneural β-adrenergic signaling with direct effect on cancer cells." (PMID 34552593, 2021). "These undifferentiated tumoral cells can be differentiated into neuron-like cells by retinoic acid and Brain-Derived Neurotrophic Factor (BDNF) treatment." (PMID 33924659, 2021). "BDNF was found to be under expressed in tumour samples while the other two were higher in tumour samples." (PMID 34685742, 2021). "However, the association among BDNF expression, tumor immunity, and PAAD prognosis remains unclear." (PMID 34777634, 2021). "Subsequently, the role of BDNF in tumor-infiltrating immune cells was determined using the TIMER database and the single-sample gene set enrichment analysis (ssGSEA) and xCell algorithm." (PMID 34777634, 2021). "Involvement of BDNF in tumor pathogenesis through TrkB has been pointed out in different cancers including lung." (PMID 34209215, 2021). "BDNF expression was significantly increased in tumor areas compared to matched normal tissues, with an IHC mean score of 2 for normal tissue and a mean score of 3 for tumor tissue." (PMID 34771682, 2021). "We found high BDNF expression in 61% of the patient tumor tissues, while high BDNF expression in matched normal tissues was observed in only 6%." (PMID 34771682, 2021). "Secretion of BDNF has been reported in tumor cells, promoting cell growth and survival of a variety of cancers including lung." (PMID 34209215, 2021). "It has been shown that the level of BDNF is positively correlated with tumor metastasis and poor prognosis, and binding of BDNF to its receptor TrkB can promote the proliferation, invasion, and metastasis of tumors." (PMID 33628340, 2021). "In our analysis, BDNF was found to be down regulated in tumours, while HLA-A was upregulated in tumours." (PMID 34685742, 2021). "Accordingly, circ_0000006 absence repressed tumor growth by regulating miR-646 and BDNF expression in vivo." (PMID 34717683, 2021). "We further evaluated the best fit multivariate Cox models using the three-protein signature (CD66b, CysLT1R, BDNF) in tumor tissues from the univariate model to better predict OS and separate the high-risk patient group (HR = 1.72, p = 0.01)." (PMID 34771682, 2021). "For example, most of the available literature has demonstrated that BDNF can promote tumor development and predict unfavorable prognosis in pan-cancer." (PMID 34777634, 2021). "Some of these factors, such as brain-derived neurotrophic factor (BDNF) and TGF-β1, can promote EMT-like phenotypes, in both normal cells and in tumor cells bearing mutations in oncogenes and tumor suppressor genes." (PMID 34140545, 2021). "To investigate the importance of BDNF expression in CC, we stained our CC cohort with patient tumor samples and their matched corresponding normal mucosa with the BDNF antibody." (PMID 34771682, 2021). "The role of BDNF in tumor-infiltrating immune cells was determined using the Tumor Immune Estimation Resource database and the single-sample gene set enrichment analysis and xCell algorithm." (PMID 34777634, 2021). "CD66b and BDNF expression was significantly higher in patient tumor tissues than in the matched normal mucosa." (PMID 34771682, 2021). "Tumor cells were reported to secrete BDNF, and both BDNF and TrkB have been shown to be upregulated in a wide variety of tumors." (PMID 34209215, 2021). "Our results suggests that high CD66b neutrophil content in the tumor microenvironment increase the BDNF production via CysLT1R signaling, which led to poor survival of patients with CRC." (PMID 34771682, 2021). "Our study confirms the significantly higher BDNF concentration in patients with TNM stage IV tumours, but we didn’t find any significant differences in neurotrophin concentration related to tumour size." (PMID 34395067, 2021).
tumor (continued). "We explored the correlation between serum levels of BDNF and several pathological features, such as tumor differentiation and TNM staging." (PMID 33628340, 2021). "At the mRNA expression level, BDNF expression was downregulated in nine types of tumors compared to normal tissues, whereas others were remarkably elevated in tumor tissues." (PMID 34777634, 2021). "EE is also known to suppress tumor growth by increasing the production of brain-derived neurotrophic factor (BDNF) in the hypothalamus, which reduces leptin production via sympathetic β-adrenergic receptors." (PMID 34745135, 2021). "Single studies concerning various cancers showed that Pro-NGF/NGF (nerve growth factor), BDNF (brain-derived neurotrophic factor), Ephrin B1, neuroligin-3, pleiotrophin, semaphorin 4F were involved in the regulation of tumor innervation." (PMID 34277455, 2021). "BDNF and TrkB are overexpressed in head and neck SCC and have been implicated in tumor progression and invasiveness in patients with head and neck SCC." (PMID 34885121, 2021). "In preclinical models, BDNF promotes tumor growth by neovascularization, in a murine tumor model produces large and hyper-vascularized tumors (BNL cells in nude mice)." (PMID 32555170, 2020). "In response to adrenaline, tumor cells produce and secrete BDNF in the TME, a fact that leads to tumor innervation by signaling through host neurotrophic receptor tyrosine kinase 2 receptors." (PMID 33339112, 2020). "NAS within tumours and released from tumour microenvironment cells activates the brain-derived neurotrophic factor (BDNF) receptor, TrkB, thereby increasing the survival and proliferation of cancer stem-like cells." (PMID 33375613, 2020). "In ovarian cancer, there is a feedforward loop through which adrenergic signaling can induce BDNF secretion from tumor cells via a β-adrenergic receptor 3 (ADRβ3)/cAMP/Epac/JNK-dependent manner." (PMID 33392191, 2020). "We demonstrated that BDNF promoted tumor formation and induced prosurvival and prometastatic gene expression in vivo." (PMID 32471985, 2020). "Our previous study demonstrated that BDNF promotes the migratory activity of both tumour cells (MDA-MB-231) and endothelial cells (HUVECs) via a number of autocrine and paracrine regulation pathways, respectively." (PMID 32415115, 2020). "This factor is neuroprotective, improving neuronal survival, and synaptic function and plasticity; conversely, in GBM, BDNF promotes tumor cell stemness." (PMID 33328891, 2020). "Another study found BDNF- and TrkB-positive tumor cells in 6 out of 27 and 18 out of 29 samples, respectively." (PMID 32906676, 2020). "A reduction in tumor growth of the primary tumor but also at the metastatic level is observed when using adenovirus inducing the expression “brain‐derived neurotrophic factor”36 or MBP‐166 (Myelin Basic Protein 1)." (PMID 33026171, 2020). "It is clear that localized delivery of these drugs to the target organs will be critical for achieving maximal efficacy, such as activating TrkB in neurons with BDNF mimics or reducing tumor burden and preventing metastasis with TrkB antagonists." (PMID 32471985, 2020). "Many reports explained that BDNF along with receptor, Tropomyosin receptor kinase B is found to be upregulated in many tumors but recently it has been investigated that BDNF has immuno-augmentation properties and participates in anti-tumor response." (PMID 33473259, 2020). "Among them, the nerve growth factor (NGF) and the brain-derived neurotrophic factor (BDNF) cause axonal chemoattraction, and IL-6, IL-8, IL1b, and CCL5 foster tumor-associated hyperalgesia." (PMID 30825056, 2019).
tumor (continued). "In a co-culture model, we evidenced that inflammatory cytokines are upregulated in tumor cells co-cultured with fibroblasts, and at the same time, the fibroblasts were activated and produced increased levels of BDNF." (PMID 30641914, 2019). "We show that E2-upregulated BDNF in ER+ astrocytes and cancer cells activated TrkB signaling and increased the invasiveness and tumor-initiating capacity of TNBC cells in vitro." (PMID 30796353, 2019). "Brain-derived neurotrophic factor was sufficiently available either in normal or in tumor tissue and also in cultured HNSCC cell lines." (PMID 30641914, 2019). "With the major role of the BDNF/TrkB axis in angiogenesis and in its relation to endothelial cell survival, several research groups agree, it is indeed an important contributor to tumor progression." (PMID 30641914, 2019). "Regarding the mechanisms driving TRKB and BDNF upregulation in tumor cells, hypoxia is thought to be one of the key factors in the tumor environment." (PMID 29861866, 2018). "In most cases, the expression levels of TRKB and BDNF were both low (TRKBlow/BDNFlow) in WD-OSCC tumor cells, whereas they were both higher (TRKBhigh/BDNFhigh) in MD and PD-OSCC tumor cells." (PMID 29861866, 2018). "To investigate this relationship, we assessed the correlations between 2-year disease-free survival and expression levels of TRKB, BDNF, or both, as well as tumor cell differentiation, using the Kaplan–Meier method." (PMID 29861866, 2018). "In this study, we describe a new relationship between TRKB/BDNF expression and tumor differentiation in patients with OSCC, and propose TRKB as a potential therapeutic target for OSCC, especially for PD-OSCC." (PMID 29861866, 2018). "The current study open news avenues to further dissect the potential driving mechanisms and functional consequences of the reduced levels of AKT1, ERK1/2, NPAS4 and BDNF in tumor brain, especially within the concept of aging." (PMID 29556248, 2018). "In this study, we used the human OSCC tissues to examine the correlations between TRKB/BDNF expression, tumor differentiation, and clinicopathologic features in patients with OSCC." (PMID 29861866, 2018). "In our study, we saw significant downregulation of BDNF in PR+BC tumor-bearing treated and untreated mice and a trend towards downregulation in tumor-bearing TNBC animals." (PMID 29179434, 2017). "Going forward, we would seek to examine the mechanisms of tumor and chemotherapy-induced effects on BDNF levels in conjunction with miRNA." (PMID 29179434, 2017). "Long recognized as an important oncogenic factor in a neurogenic context, when the TrkB signaling pathway involving the neurotrophic factor BDNF is activated in other tumor types, tumor cell proliferation, invasion, and metastatic potential are all stimulated." (PMID 28725636, 2017). "While some studies suggested that tumor-derived BDNF functioned as an autrocrine and paracrine ligand, this was not evident in HNSCC." (PMID 28966935, 2017). "Our data suggest that CAFs play a complex role in tumor progression that can be modulated by manipulation of the BDNF intercellular signaling system, mediated in part through alterations in pro-lymphangiogenic cascade." (PMID 28966935, 2017). "MiR-107 functions as a tumor suppressor in NSCLC by targeting brain-derived neurotrophic factor and indirectly regulating the PI3K/AKT signaling pathway." (PMID 28496005, 2017). "Previous studies have revealed roles for BDNF-TrkB in malignant transformation, tumor progression, metastasis, angiogenesis, and therapy resistance." (PMID 28966935, 2017). "Nevertheless, controversy still exists as to the exact role of BDNF in tumor suppression and promotion." (PMID 28604807, 2017). "The present study investigated the impact of two survival pathways—neurotrophic factors (TrkB/BDNF) and autophagy—on cell fate and tumour evolution." (PMID 28597984, 2017).
tumor (continued). "We further analyzed the impact of CAFs on the development of metastasis, and found that when BDNF signaling was modulated in the tumor microenvironment, regional metastasis and metastatic efficiency were impaired." (PMID 28966935, 2017). "These two rescue experiments further established the direct regulation of cancer cell migration in the tumor microenvironment through a BDNF-directed CAF-tumor interface." (PMID 28966935, 2017). "To extend our findings in a relevant animal model, we next evaluated the impact of altered BDNF function in the tumor microenvironment." (PMID 28966935, 2017). "The aim of this study was to investigate the role of BDNF on the tumor cell microenvironment, namely, the cancer cell-endothelial cell interaction of TNBC cells." (PMID 28604807, 2017). "In a set of 71 HNSCC tumor patients, BDNF expression was increased (≥ +1 score) in 17% of tumors that were analyzed." (PMID 28966935, 2017). "We noted that BDNF levels were strongly downregulated in PR+BC tumor-bearing treated and untreated animals; however, TNBC treated and untreated animals exhibited only a trend." (PMID 29179434, 2017). "As our experimental evidence revealed an important regulatory role for BDNF in the tumor microenvironment, we sought to determine the clinical relevance of BDNF as a marker of metastasis in HNSCC." (PMID 28966935, 2017). "In Matrigel invasion experiments, tumor cells exposed to BDNF-depleted CAF media has significantly decreased cellular invasion compared to media from non-targeted CAFs." (PMID 28966935, 2017). "The expression levels of the nociceptive mediators NGF and BDNF were higher than those in the tumor cell line bmMDA under acidosis, and of cells of neuronal origin at pH 7.4." (PMID 28903357, 2017). "We found that astrocyte-derived BDNF in the neural niche is important for initial tumor cell colonization and proliferation of breast-to-brain metastasis (BBM) cells." (PMID 28446206, 2017). "Using pharmacological and genetic alterations, we mechanistically demonstrate the critical importance of BDNF-TrkB signaling in the tumor microenvironment." (PMID 28966935, 2017). "We found that BDNF knockdown inhibited tumor growth and the expression of the lymphatic vessels marker LYVE-1." (PMID 28771226, 2017). "Accordingly, it was of interest and is important that the role of BDNF in the tumor cell microenvironment is investigated." (PMID 28604807, 2017). "Tumor cells exposed to BDNF-depleted CAF-CM (siRNA-BDNF) had a 50–75% reduction of migration and invasion, compared to a non-targeting construct." (PMID 28966935, 2017). "In this study, we demonstrate the important role of human tumor-derived CAFs in mediating tumor metastasis that is mechanistically driven by the BDNF-TrkB signaling pathway." (PMID 28966935, 2017). "This study focuses on inhibition of NTs (TrkB/BDNF) and/or autophagy, which are two survival‐signaling pathways and shows the efficiency of the twin treatment, which largely contribute to reduce tumour growth." (PMID 28597984, 2017). "Using the MTT cell viability assay in vitro, we observed that cotreatment with BDNF clearly enhanced the chemosensitivity of NCI-H69 tumor cells to Cisplatin and induced the downregulation of ABCG2." (PMID 27852063, 2016). "The mechanism of BDNF pathway-mediated resistance to the most commonly used anti-tumour drugs in NB (cisplatin, vinblastine, etoposide and doxorubicin) has been described." (PMID 27256407, 2016). "Immunostaining assays for pro-BDNF is comparable to results obtained for both mature and immature BDNF indicating that pro-BDNF was highly expressed in most tumor samples as in normal tissues." (PMID 27120782, 2016). "We also tested the expression of BDNF in 33 NSCLC specimens by immunohistochemical assay and found that in 19/33 (57%) samples, the expression of BDNF was higher in the tumor samples than in the adjacent normal controls." (PMID 27456333, 2016).